MICB (MHC class I polypeptide-related sequence B)
Diseases named in the same sentence as MICB in open-access papers (continued):
Sharing a sentence is not in itself a finding about the gene and the disease.
glioblastoma (3 papers, 2018 to 2019). The most malignant astrocytic tumor (WHO grade IV). "Tumor-associated myeloid cells and circulating monocytes in glioblastoma patients were found to upregulate the human NKG2D ligands ULBP1 and MICB." (PMID 29757143, 2018). "Cell surface expression of the main ligands for the NKG2D receptor (MICA, MICB, ULBP1, ULBP2, and ULBP3) on the glioblastoma cell lines, U-251MG, T98G, and U-87MG, was assessed by flow cytometry." (PMID 31288857, 2019). "Next, the co-expression of the glioblastoma stem cell marker NESTIN and NKG2DLs (MICA, MICB, ULBP1, ULBP2, ULBP3) in these suspended cell spheres was assessed by flow cytometry." (PMID 31288857, 2019). "MICB and ULBP1 were also shown to be upregulated on healthy monocytes from glioblastoma patients in response to tumor-derived lactate dehydrogenase." (PMID 29483917, 2018).
multiple sclerosis (3 papers, 2011 to 2024). A progressive autoimmune disorder affecting the central nervous system resulting in demyelination. "Remarkably, it was recently reported that in multiple sclerosis (MS) patients, serum MICB levels are increased and are associated with relapse." (PMID 26909604, 2016).
osteosarcoma (3 papers, 2021 to 2025). A usually aggressive malignant bone-forming mesenchymal neoplasm, predominantly affecting adolescents and young adults. "Both ULPB1 and MICA/MICB transcripts are significantly (p < 0.01) upregulated in osteosarcoma tissues compared to normal tissues, suggesting enhanced baseline stress levels in osteosarcoma tumor cells due to their malignant nature." (PMID 40969756, 2025). "Interestingly, some NKG2D ligands (MICA, MICB, ULBP-2 and ULBP-3) are secreted from NSCLC, osteosarcomas and gastric cancer cells and may be shed by MMP-mediated cleavage." (PMID 34638439, 2021).
ovarian carcinoma (3 papers, 2017 to 2023). A malignant neoplasm originating from the surface ovarian epithelium. "The results indicated that a high expression of MICB mRNA was significantly associated with poor PFS in ovarian cancer patients, including ovarian serous carcinoma and ovarian endometrioid adenocarcinoma patients." (PMID 30926680, 2019). "And MICB was co-up-regulated with SFN in ovarian cancer, which was confirmed by the GEPIA database, suggesting that SFN could be associated with the MICB in ovarian cancer." (PMID 30926680, 2019). "First, we investigated the expressions and prognosis value of SFN and MICB in ovarian cancer from several public databases." (PMID 30926680, 2019). "Afterward, the prognostic value of MICB in ovarian cancer was examined via the Kaplan–Meier survival plots." (PMID 30926680, 2019). "In summary, SFN and its coexpressed gene MICB were significantly increased in multiple types of ovarian cancer." (PMID 30926680, 2019). "In human ovarian carcinoma SKOV3 and A2780 cells, the expression of SFN and its coexpression gene MICB were also increased at protein and mRNA levels compared with the normal ovarian epithelial cells." (PMID 30926680, 2019). "To assess the cytotoxic activity of CD8+ CIK cells on ovarian cancer cells, we screened a panel of ovarian cancer cell lines for the expression of NKG2D ligands including MICA, MICB and ULBP1-4 by qPCR." (PMID 28426690, 2017).
prostate carcinoma (3 papers, 2019 to 2025). A carcinoma that arises from epithelial cells of the prostate gland. "Using bi-transgenic TRAMP mouse models of prostate cancer, soluble MICB was shown to promote carcinoma progression by depleting peripheral NK cells, whereas membrane-restricted MICB supported long-term tumor-free survival through sustained NKG2D-mediated anti-tumor immunity." (PMID 40243581, 2025). "Since tumor cells are recognized by NK cells through an interplay of activating and inhibitory ligands, we decided to evaluate the expression of CD155, CD112, MICA, MICB, ULBP1-2-5-6, PDL-1, and B7-H6 on 22Rv1, LNCaP, and DU145 prostate cancer cells." (PMID 35465350, 2022). "We observed that CD155 and CD112 were expressed at higher levels than MICA, MICB, ULBP1-2-5-6, PDL-1, and B7-H6 on all the prostate cancer cells (∗∗∗p < 0.001)." (PMID 35465350, 2022).
rheumatoid arthritis (3 papers, 2014 to 2025). A chronic, systemic autoimmune disorder characterized by inflammation in the synovial membranes and articular surfaces. "In rheumatoid arthritis, MICA and MICB are aberrantly expressed in pathological tissue from affected joints and could be involved in the continuation of the autoreactive process." (PMID 24565339, 2014).
squamous cell carcinoma (3 papers, 2023 to 2025). A carcinoma arising from squamous epithelial cells. "In most malignant tumors, the KIFscore was found to be positively correlated with ULBP1, MICB, and CD276, among which, CD276 expression was reported to enable squamous cell carcinoma stem cells to evade immune surveillance." (PMID 37711200, 2023).
acute hepatitis A (2 papers, 2018 to 2021). "Among patients with different stages of hepatitis, asymptomatic individuals have higher MICB serum levels, whereas liver cirrhosis patients have lower MICB serum levels (P < 0.0001) compared to those in other patient groups." (PMID 34532296, 2021). "Recently, it has been reported that in acute hepatitis A patients, NKG2DhighCD8+ T cells induced by IL15 promote damage of liver tissue expressing NKG2D ligands such as MICA and MICB." (PMID 30333822, 2018).
autoimmune conditions (2 papers, 2016 to 2026). "Subsequent validation of these results in animal models will provide indisputable evidence that our designed Anti-MICB-CAR-NK cells can effectively trigger autoimmunity within the anti-tumor mechanism, resulting in the elimination of multiple solid tumors." (PMID 41516373, 2026). "Elevated serum MICA and MICB were reported in cancer and autoimmune conditions." (PMID 26909604, 2016).
celiac disease (2 papers, 2022 to 2023). An autoimmune genetic disorder with an unknown pattern of inheritance that primarily affects the digestive tract. "Plasma MICB levels were found to be genetically linked with higher CRC risk, as well as higher risk of gastrointestinal malabsorption disorders, including celiac disease and non-celiac intestinal malabsorption." (PMID 38049731, 2023).
colitis (2 papers, 2018 to 2021). Inflammation of the colon. "Colitis increases the expression of the human nonclassical MHC class I molecules MICA and MICB on intestinal epithelial cells, resulting in the migration of CD8+ T cells into the inflamed intestine." (PMID 33513946, 2021).
metastatic melanoma (2 papers, 2016 to 2021). A melanoma that has spread from its primary site to another anatomic site. "Serum CEACAM1, MICA and MICB concentrations were measured by ELISA in ∼50 subjects of each group: acute pericarditis (AP), recurrent pericarditis (RP) and lupus (SLE) patients, metastatic melanoma patients as well as healthy donors." (PMID 26909604, 2016). "MICA and MICB were strongly elevated in SLE patients and in patients with metastatic melanoma, irrespective of neoplastic pericardial involvement." (PMID 26909604, 2016). "The absence of MICB and ULBP-1 in baseline serum, signifying that MICB and ULBP-1 had reduced shedding, is significantly correlated with improved survival in patients with metastatic melanoma treated with immune checkpoint blockade." (PMID 33802954, 2021).
acute appendicitis (1 paper, 2025). "And we found that five genes C4A, FLOT1, LINC00243, MICB, and PRSS16 shared the same tissues between MDD and acute appendicitis." (PMID 41438618, 2025). "Additionally, through the colocalization analysis, we identified five shared pleiotropic genes between MDD and acute appendicitis: C4A, FLOT1, LINC00243, MICB, and PRSS16." (PMID 41438618, 2025). "Finally, the colocalization analysis identified five shared pleiotropic genes for MDD and acute appendicitis: C4A, FLOT1, LINC00243, MICB, and PRSS16." (PMID 41438618, 2025). "Finally, we defined three shared genes: PRSS16, ZNF602P, and ZNF204P by TWAS and nine pleiotropic genes C4A, FLOT1, LINC00243, MICB, and PRSS16 by colocalization analysis between MDD and acute appendicitis." (PMID 41438618, 2025).
acute lung injury (1 paper, 2025). A condition of lung damage that is characterized by bilateral pulmonary infiltrates (pulmonary edema) rich in neutrophils, and in the absence of clinical heart failure. "We have shown NK cells are central to lung transplant acute lung injury (ALI) via NKG2D activation, and increased MICB in bronchoalveolar lavage predicts ALI severity." (PMID 40608426, 2025).
astrocytoma (1 paper, 2011). "Constitutive levels of NKG2D ligands are low in most cells, thus, to examine the effect of U21 upon the surface expression of the NK ligands, we generated U373 astrocytoma cell lines individually stably expressing ULBP1, ULBP2, ULBP3, MICA, or MICB, using retrovirus-mediated gene transfer." (PMID 22102813, 2011).
childhood asthma (1 paper, 2024). "Elevated levels of seven proteins (TLR4, UBP25, CBR1, Rac GTPase‐activating protein 1 [RGAP1], IL‐21, MICB, and PDE4D) and decreased levels of three proteins (GSTO1, LIRB4 and PIGF) were associated with an increased risk of childhood asthma." (PMID 38730525, 2024). "Our analysis focused on four proteins, IL‐21, MICB, PDE4D, and RGAP1, which exhibited effects in both MR analyses involving risk factors and childhood asthma outcomes." (PMID 38730525, 2024). "Based on the genetic data of 4419 (of 4489) plasma proteins from UK Biobank, our study presents compelling evidence linking 10 plasma proteins (GSTO1, LIRB4, PIGF, IL‐21, MICB, PDE4D, RGAP1, TLR4, UBP25 and CBR1) to childhood asthma." (PMID 38730525, 2024). "Hence, the specific mechanisms by which MICB, PDE4D, and IL‐21 proteins affect the onset of childhood asthma will require further experimental evidence for elucidation." (PMID 38730525, 2024).
Cognitive impairment (1 paper, 2025). Abnormal cognition is characterized by deficits in thinking, reasoning, or remembering. "IDO1 plays a crucial role in regulating immune responses and inflammation, potentially contributing to cognitive deterioration in PD patients, whereas MICB modulates natural killer and T cell activity, suggesting a complex immune regulatory mechanism underlying cognitive impairments." (PMID 40008429, 2025).
dementia (1 paper, 2018). Loss of intellectual abilities interfering with an individual's social and occupational functions. "We identified altered proteins in AD not common to other dementias like the E3 ubiquitin-protein ligase TOPORS, Layilin and MICB, and validated the association to AD of the previously controverted proteins DDIT3 and the E3 ubiquitin-protein ligase XIAP." (PMID 29541381, 2018).
depression (1 paper, 2025). "MICB, or MHC Class I Polypeptide‐Related Sequence B, is crucial for GI tract function and has recently been identified as a risky gene for depression among perinatal populations." (PMID 41438618, 2025).
diabetic nephropathy (1 paper, 2024). "Besides, MICB may promote the development and progression of diabetic nephropathy." (PMID 38898508, 2024).
endometrial tumor (1 paper, 2021). "We analyzed the surface expression of MICA, MICB, CD112, CD155, and B7-H6 on target endometrial tumor cell lines including Ishikawa, KLE and RL95-2 by flow cytometry." (PMID 34691070, 2021).
esophageal adenocarcinoma (1 paper, 2021). A malignant tumor with glandular differentiation arising predominantly from Barrett mucosa in the lower third of the esophagus. "Transcriptomics showed that the combination of SLC26A9 and the other four genes, SINHCAF, MICB, KRT19, and MT1X, became a gene signature that predicts the overall survival of esophageal adenocarcinoma." (PMID 35008199, 2021).
essential hypertension (1 paper, 2017). Hypertension that presents without an identifiable cause. "Hcmv-miR-UL112-3p targets MICB and IRF-1, which play critical roles in immunological, inflammatory, and anti-infection responses, and these proteins have a close relationship with essential hypertension." (PMID 28592251, 2017).
gastritis (1 paper, 2024). Inflammation of the stomach. "In parallel, the NKG2D-L MICB was significantly upregulated in gastritis and adenocarcinoma cases, suggesting a dysregulation of the NKG2D system." (PMID 38318189, 2024).
Hematuria (1 paper, 2023). The presence of blood in the urine. "However, we also observed that lower levels of plasma MICB are associated with lower hematuria risk." (PMID 38049731, 2023).
Hypertension (1 paper, 2017). The presence of chronic increased pressure in the systemic arterial system. "Hcmv-miR-UL112-3p targets IRF-1 and MICB, which are two key molecules in immunological, inflammatory and anti-infective responses, and IRF-1 and MICB repression by hcmv-miR-UL112-3p may be a unifying mechanism that evades the host response in the pathogenesis of hypertension." (PMID 28592251, 2017).
Infertility (1 paper, 2025). "In the non-ART sample, we identified genome-wide significant fetal effects on fetal survival for SNPs within regions harboring genes relevant to infertility and fetal development, such as MDC1, MICB, HCP5, and NOTCH4." (PMID 41325449, 2025).
leprosy (1 paper, 2015). Leprosy is a chronic infectious disease affecting primarily the skin and peripheral nervous system. "A study analyzed exon 5 of the MICA gene and intron 1 of MICB in families of Southern India who developed PB leprosy and showed that MICA*5A 5.1, MICB*CA16 and MICB*CA19 were associated with the disease." (PMID 26793196, 2015). "Summary of associations between genes of innate immune response MICA, MICB, KIR, TNF, LTA, BAT1, IFNG, and leprosy." (PMID 26793196, 2015).
liver cancer (1 paper, 2024). An epithelial or non-epithelial malignant neoplasm that arises from the liver. "The HDAC inhibitor MS-275 epigenetically modified exosomes secreted by human liver cancer cells, increasing the expression of MICA, MICB, and heat shock protein 70, and enhancing the cytotoxic effects of NK cells." (PMID 38915093, 2024).
liver diseases (1 paper, 2015). "Also, soluble MICB serum levels were associated with various diseases such as multiple sclerosis, liver diseases and cancers." (PMID 25626490, 2015). "The study investigated the prognostic role of soluble MICB (sMICB) protein in the progression of HBV-related liver diseases and to HBV-related HCC treatment." (PMID 25626490, 2015).
lymphoma (1 paper, 2014). A malignant (clonal) proliferation of B- lymphocytes or T- lymphocytes which involves the lymph nodes, bone marrow and/or extranodal sites. "The NKG2D ligands MICA/MICB/ULBP are stress molecules expressed on tumor cells, and secreted at high levels in HIV patients, leading to down-regulated NKG2D expression on NK and impaired anti-lymphoma cytotoxicity." (PMID 25908934, 2014).
malignant glioma (1 paper, 2014). A grade III or grade IV glioma arising from the central nervous system. "Additionally, transforming growth factor-beta (TGF-beta) selectively downregulates the expression of MICA, ULBP2, and ULBP4, but not MICB, ULBP1, or ULBP3, in malignant glioma cells." (PMID 24885711, 2014).
membranous nephropathy (1 paper, 2024). "In addition, we observed that BTN3A2, BTN3A3, and MICB decreased the risk of membranous nephropathy, but sRAGE and AIF1 increased this risk." (PMID 38898508, 2024).
myelodysplastic syndrome (1 paper, 2025). A clonal hematopoietic disorder characterized by dysplasia and ineffective hematopoiesis in one or more of the hematopoietic cell lines. "The other study was a phase I clinical trial of MICA & MICB KO anti-NKG2D CAR T cells in six patients with relapsed/refractory myelodysplastic syndrome (MDS)/AML." (PMID 41354926, 2025).
myocardial infarction (1 paper, 2016). Gross necrosis of the myocardium, as a result of interruption of the blood supply to the area, as in coronary thrombosis. "Approximately a third of the idiopathic and autoimmune RP patients, and 50% of the post pericardiotomy and post myocardial infarction RP patients exhibited high values of MICB." (PMID 26909604, 2016).
nephrotic syndrome (1 paper, 2024). A collection of symptoms that include severe edema, proteinuria, and hypoalbuminemia; it is indicative of renal dysfunction. "Additionally, DQA2, C4a, and MICB were protectively associated with both chronic glomerulonephritis and nephrotic syndrome." (PMID 38898508, 2024).
non-alcoholic fatty liver (1 paper, 2018). A benign form of fatty non-alcoholic fatty liver disease where the disease has not yet progressed to the inflammation of liver. "Patients diagnosed with non-alcoholic fatty liver (NAFL) or non-alcoholic steatohepatitis (NASH) showed significantly increased expression of MICA and MICB on hepatocytes." (PMID 30150983, 2018).
non-small cell lung carcinoma (1 paper, 2018). A group of at least three distinct histological types of lung cancer, including non-small cell squamous cell carcinoma, adenocarcinoma, and large cell carcinoma. "Cisplatin was previously reported to induce the MICA and MICB expression in non-small-cell lung cancer A549 cell line, through DNA stress-induced ATM-ATR signalling, resulting in enhanced sensitivity to NK cell-mediated cytotoxicity." (PMID 29805983, 2018).
ovarian endometrioid adenocarcinoma (1 paper, 2019). An endometrioid adenocarcinoma arising from the ovary. "Besides, high expression of MICB predicted worse PFS in both ovarian serous carcinoma and ovarian endometrioid adenocarcinoma patients." (PMID 30926680, 2019).
ovarian serous adenocarcinoma (1 paper, 2019). An adenocarcinoma that arises from the ovary and is characterized by the presence of malignant epithelial cells that, in well differentiated tumors, resemble the epithelium of the fallopian tube or, in poorly differentiated tumors, show anaplastic features and marked nuclear atypia. "Through investigating patient with ovarian serous adenocarcinoma data in TCGA database using GEPIA database, the positive correlation between MICB and SFN was confirmed." (PMID 30926680, 2019). "The results of our analysis revealed that MICB expression had an obviously increased level in ovarian serous adenocarcinoma and ovarian serous cystadenocarcinoma compared with the normal tissues." (PMID 30926680, 2019). "In our studies, we also demonstrated that MICB was notable up-regulated in ovarian serous adenocarcinoma and ovarian serous cystadenocarcinoma compared with the normal tissues." (PMID 30926680, 2019).
pericarditis (1 paper, 2016). An inflammatory process affecting the pericardium. "This argues against a significant diagnostic role for MICA and MICB in pericarditis." (PMID 26909604, 2016). "Collectively, these prompted the investigation of serum CEACAM1, MICA and MICB in pericarditis patients." (PMID 26909604, 2016). "Here we investigate the involvement of serum CEACAM1, MICA and MICB, proteins that can be induced in damaged or inflamed tissues, in pericarditis patients." (PMID 26909604, 2016). "As some of these conditions may play a role in pericarditis, upregulation of CEACAM1, MICA or MICB could be anticipated in situ." (PMID 26909604, 2016). "Serum MICA and MICB levels were elevated in some of the pericarditis patients, but without reaching statistical significance or efficient ROC curves." (PMID 26909604, 2016).
rectal cancer (1 paper, 2020). A primary or metastatic malignant neoplasm that affects the rectum. "However, for patients with rectal cancer, the survival curves of MICB expression were significant (P < 0.001)." (PMID 32306128, 2020).